FPGT (fucose-1-phosphate guanylyltransferase)
Description:
Catalyzes the formation of GDP-L-fucose from GTP and L-fucose-1-phosphate. Functions as a salvage pathway to reutilize L-fucose arising from the turnover of glycoproteins and glycolipids.
Synonyms: GFPP
Tractability: PROTAC: ubiquitination databases record sites on it; its protein half-life has been measured.
Gene: Protein-coding gene on chromosome 1 (74,198,238 to 74,234,086, forward strand). Ensembl gene ENSG00000254685.
Subcellular location: Cytoplasm
Subcellular location (Human Protein Atlas): Vesicles
Pathways (Reactome):
Metabolism of proteins: GDP-fucose biosynthesis
Gene Ontology:
Molecular function: fucose-1-phosphate guanylyltransferase activity; transferase activity, transferring phosphorus-containing groups
Biological process: fucose metabolic process; GDP-L-fucose biosynthetic process; GDP-L-fucose salvage
Cellular component: cytoplasm; cytosol
Genetic constraint (gnomAD): Loss-of-function variants: 30 observed, 36.39 expected, observed/expected ratio (o/e) 0.82, 90% interval 0.62 to 1.12. The upper end of that interval is the gene's LOEUF score, 1.12, which puts it in group 4 of 6, group 1 being the genes least tolerant of losing a copy. Missense variants: 634 observed, 605.71 expected, observed/expected ratio (o/e) 1.05, 90% interval 0.98 to 1.12. Synonymous variants: 241 observed, 223.57 expected, observed/expected ratio (o/e) 1.08, 90% interval 0.97 to 1.2.
Homologues: Orthologues: chimpanzee FPGT (99% identical), pig FPGT (86% identical), dog FPGT (86% identical), guinea pig FPGT (81% identical), rat Fpgt (74% identical), mouse Fpgt (73% identical), tropical clawed frog fpgt (56% identical), zebrafish fpgt (52% identical), Caenorhabditis elegans K03H1.13 (23% identical).
Diseases named in the same sentence as FPGT in open-access papers:
FPGT is named in the same sentence as 5 diseases in open-access papers, as found by Europe PMC text mining. Sharing a sentence is not in itself a finding about the gene and the disease. The quoted sentences say what the papers report.
myocarditis (1 paper, 2021). Myocarditis is a condition that is characterized by inflammation of the heart muscle (myocardium). "Candidate gene analysis revealed fucose-1-phosphate guanylyltransferase (Fpgt) and Tnni3k as promising targets for Vms1 (viral myocarditis susceptibility 1), which plays a role in the pathogenesis of coxsackievirus B3 infection, the most common cause of myocarditis." (PMID 34203974, 2021).
viral myocarditis (1 paper, 2013). Myocarditis that is caused by an infection with a viral agent. "The locus including both TNNI3K and FPGT genes was found to be responsible for susceptibility to viral myocarditis in mice." (PMID 23915065, 2013).
FPGT also shares sentences with these, for which no sentence is quoted: cancer (1 paper); poisoning (1); tumor (1).